IL6R (interleukin 6 receptor)
Diseases named in the same sentence as IL6R in open-access papers (continued):
Sharing a sentence is not in itself a finding about the gene and the disease.
endometriosis (3 papers, 2020 to 2024). The growth of functional endometrial tissue in anatomic sites outside the uterine body. "Macrophages in endometriosis produce IL-6, which is implicated in monocyte recruitment and, together with its receptor (IL-6R), regulates endometrial stromal cell growth in vitro." (PMID 39458478, 2024).
esophageal cancer (3 papers, 2013 to 2020). A primary or metastatic malignant neoplasm involving the esophagus. "Similar to other series, we found that IL-6 and IL-6R were detected in both esophageal cancer specimens and esophageal carcinoma cell lines." (PMID 23561329, 2013). "Circulating factors such as C-reactive protein (CRP), soluble interleukin-6 receptor (sIL-6R) and vascular endothelial growth factor (VEGF) have demonstrated prognostic potential in esophageal cancer, however most studies to date have focused on squamous cell type esophageal tumors." (PMID 33202734, 2020).
fatty liver disease (3 papers, 2019 to 2023). A reversible condition wherein large vacuoles of triglyceride fat accumulate in liver cells via the process of steatosis. "Indeed, blocking the IL-6R was able to inhibit adipose browning and its associated hepatic steatosis in post-burned mice." (PMID 31740668, 2019). "The therapeutic effects of IL-6R blocker treatment in the adipose tissue of post-burn mice also carried over to the liver, where we observed reductions in markers of hepatic steatosis." (PMID 31740668, 2019).
head and neck cancer (3 papers, 2021 to 2024). A primary or metastatic malignant neoplasm affecting the head and neck. "Taken together, these findings imply that pharmacological suppression of IL-6R may represent a feasible approach to surmount CSC-mediated chemoresistance in head and neck cancer." (PMID 39272862, 2024). "In summary, these data suggest that therapeutic inhibition of IL-6R might be a viable strategy to overcome CSC-mediated chemoresistance in head and neck cancer." (PMID 34689150, 2021). "Blockade of IL-6R with a humanized monoclonal antibody (Tocilizumab; TCZ) is sufficient to inhibit Bmi-1 expression and overcome the intrinsic chemoresistance of head and neck cancer stem cells." (PMID 36091805, 2022).
hyperglycaemia (3 papers, 2018 to 2019). "Hyperglycemia induced increased basal IL-6Rα mRNA expression as compared to normal glucose (NG) control." (PMID 31073533, 2019). "Thus, it suggests that the axis of both IL‐6/IL‐6R and IL‐6/gp130 is harmful to podocyte under hyperglycaemia." (PMID 28881473, 2018).
keloid (3 papers, 2009 to 2024). An irregularly shaped, elevated mark on the skin caused by deposits of excessive amounts of collagen during wound healing. "Three major limitations of our study are (i) differences between various ethnic groups in the frequency of the analyzed IL6 and IL6R variants, (ii) differences between ethnic groups in the occurrence of the clinical phenotype of keloids, and (iii) the relatively small size of our sample." (PMID 38791322, 2024). "This raises the question of whether the rs1800797, rs1800796, and rs1800795 polymorphisms in the IL6 gene promoter or the functional rs2228145 polymorphism of the IL6R gene predispose patients of European descent to keloid formation." (PMID 38791322, 2024). "Particularly, an elevated level of IL-6, a critical cytokine of the TH2 cells, and its receptor IL-6R, were detected in all keloid tissues screened and further confirmed by immunohistochemical studies and Western blot analysis." (PMID 19907660, 2009). "Consistent with previous reports, we have demonstrated that IL-6 is significantly up-regulated in keloid scars versus their normal skin counterparts, and KPCs constitutively express a higher level of IL-6 and IL-6R compared to SKPs." (PMID 19907660, 2009). "The IL6 rs1800797, rs1800796, and rs1800795 and IL6R rs2228145 genotype distributions in the combined group of keloid patients and control newborns conformed to the expected Hardy-Weinberg equilibria (p = 0.364, p = 0.302, p = 0.368, and p = 0.674, respectively)." (PMID 38791322, 2024). "The rs1800797, rs1800796, and rs1800795 polymorphisms in the promoter of the IL6 gene coding for interleukin-6 and the rs2228145 polymorphism in the IL6R gene coding for the alpha subunit of the IL-6 receptor did not predispose to the occurrence of keloids in the studied group of Poles." (PMID 38791322, 2024).
lymph node metastasis (3 papers, 2021 to 2024). "Across both patient cohorts, the high IL6R expression, poor outcome patients had significantly higher numbers of lymph node metastases (LN met) (cohort 1; p = 0.003, cohort 2; p = 0.035)." (PMID 39766336, 2024).
mastocytosis (3 papers, 2016 to 2025). A clonal myeloproliferative neoplasm characterized by the proliferation and accumulation of neoplastic mast cells in one or multiple organs or organ systems. "The authors showed that homozygous carriers of the missense variant of the IL6R gene (rs 9192284 AA genotype) had a 2.5-fold lower risk for mastocytosis than those with the AC or CC genotypes." (PMID 33401724, 2021). "Recent studies have identified genetic polymorphisms in cytokine and receptor genes (IL13, IL6, IL6R, IL31, IL4R, VEGFA) and Toll‐like receptors as potential contributors to mastocytosis." (PMID 41031827, 2025). "For instance, a large Mendelian randomization study demonstrated causal links between plasma protein expression (e.g., TNFAIP3, IL6R, LAYN) and the risk of allergic diseases, suggesting that similar strategies could be applied to uncover therapeutic targets in mastocytosis." (PMID 41031827, 2025). "Our observations support the concept that therapeutic approaches that block DJ-1 transcription, including blockade of IL-6R or its signaling, may be of potential benefit in advanced mastocytosis by reducing mast cell growth at least partly through interfering with redox adaptation mechanisms." (PMID 27611333, 2016).
neuropathy (3 papers, 2023 to 2025). A disorder affecting the nervous system that manifests with pain, tingling, numbness, and/or muscle weakness. "Additionally, PN-G-treated animals also exhibited noticeably reduced expressions of p38 MAP kinase and IL-6R, the crucial factors in the neuropathy-associated inflammation." (PMID 40969950, 2025).
ovarian tumors (3 papers, 2015 to 2022). "Although a number of biological molecules related to metastasis in ovarian tumors have been elucidated, the precise role of IL-6R expression on cell membrane is undefined." (PMID 27825119, 2016).
rectal cancer (3 papers, 2021 to 2024). A primary or metastatic malignant neoplasm that affects the rectum.
sarcopenia (3 papers, 2015 to 2025). Progressive decline in muscle mass due to aging which results in decreased functional capacity of muscles. "This is the first study of which we are aware that investigates potential causal associations for IL-6 and IL-6R with sarcopenia traits using Mendelian Randomization." (PMID 38750566, 2024). "Single nucleotide polymorphisms (SNPs) were employed as genetic instruments for IL-6 and IL-6R to estimate the causal effect of sarcopenia traits." (PMID 38750566, 2024). "However, the presence of a causal relationship between IL-6, its receptor (IL-6R), and sarcopenia remains unclear." (PMID 38750566, 2024). "This is opposed by the increase of IL‐6Rα, TNFRI, and TNFII in the blood plasma of BDL mice, indicating a systemic pro‐inflammatory state that promotes sarcopenia." (PMID 39971588, 2025).
thrombosis (3 papers, 2022 to 2025). "Inflammation is closely associated with thrombosis, and IL6R’s role in modulating immune responses may impact both vascular health and blood clotting dynamics, which are critical factors in DVT risk." (PMID 40375318, 2025). "Further, in univariate logistic regression analysis, admission to ICU and use of anti-IL6/anti-IL6R and corticosteroids were predictive of thrombosis occurrence." (PMID 36028857, 2022).
urinary tract infection (3 papers, 2021 to 2025). "On other key bacterial infection endpoints, such as skin/soft tissue and urinary tract infections, we found trends toward a higher risk (similar to IL6R), although the effects were not statistically significant." (PMID 40858837, 2025). "In this study, higher level of IL6R was detected in urine of adult donkeys than in neonatal donkeys, which might indicate the higher vulnerability of urinary tract infection in neonatal donkeys compared to adult donkeys." (PMID 36585464, 2022).
vasculitis (3 papers, 2020 to 2022). "Next, to determine the role of IL-6 in LCWE-induced KD vasculitis, we examined the impact of treatment with an IL-6R antagonist antibody on disease pathogenesis." (PMID 33897686, 2021).
acute kidney injury (2 papers, 2021 to 2025). Sudden and sustained deterioration of the kidney function characterized by decreased glomerular filtration rate, increased serum creatinine or oliguria. "The inflammatory factors associated with acute kidney injury, such as IL-6, IL-6R, IL-17, and IL-33, also showed significantly decreased expression levels by DB03476 administration." (PMID 41516327, 2025).
acute myeloid leukemia (2 papers, 2021). Acute myeloid leukemia (AML) is a group of neoplasms arising from precursor cells committed to the myeloid cell-line differentiation. "The differential analysis revealed that 58% of tumors showed a moderate significant increase in relative expression of Exon 9-retaining IL6R isoform (FC ≥ 1.4—p ≤ 0.05) especially for the acute myeloid leukemia displayed a FC equal to 2.53." (PMID 34576335, 2021).
alopecia (2 papers, 2020 to 2022). Hair loss usually from the scalp. "The STAT3 GOF mutation patient received treatment with the anti-IL6R monoclonal antibody tocilizumab and achieved a stable condition with less alopecia, normal blood glucose levels and fewer infections." (PMID 32944025, 2020). "OSM (oncostatin M) and IL6R (interleukin 6 receptor) were significantly up-regulated in giant pandas with alopecia." (PMID 35413801, 2022).
aortic aneurysm (2 papers, 2017 to 2024). A ruptured aneurysm located in the wall of the proximal portion of the descending aorta proceeding from the arch of the aorta. "During the statistical evaluation of Spearman correlation data, we found medium negative correlation between the aortic aneurysm diameter and protein levels of IL-6R (rs = −0.37, p < 0.024)." (PMID 29158612, 2017).
cardiac arrest (2 papers, 2022 to 2024). Cessation of breathing and/or cardiac function. "The anti-IL-6R antibody, Tocilizumab, is cardioprotective in cardiac arrest patients." (PMID 38840141, 2024). "Our data provide evidence that in the setting of inflammation characterized by high IL-6 titers, the use of medications such as AZM + HCQ increases the arrhythmogenic risk with the potential for cardiac arrest without any significant changes in IL6R gene expression by AZM + HCQ." (PMID 35058480, 2022).
cartilage disease (2 papers, 2013 to 2023). Softening and degeneration of the CARTILAGE. "Novel treatment options for more advanced disease in patients with costochondritis associated with important lethal syndromes are proposed like anti-tumor necrosis factor treatment with adalimumab and anti-interleukin-6 receptor antibody." (PMID 24416624, 2013).
Cerebral ischemia (2 papers, 2025). Restriction of arterial blood supply to the brain associated with insufficient oxygenation to support the metabolic requirements of the tissue. "In the context of cerebral ischemia, one key target of miR-21 is the interleukin-6 receptor (IL-6R)." (PMID 40981170, 2025). "IL6 binds to IL6R, activating downstream JAK-STAT and MAPK signaling pathways, which in turn promotes the production of inflammatory factors and the infiltration of inflammatory cells, ultimately exacerbating neural damage following cerebral ischemia." (PMID 39847586, 2025).
cholangiocarcinoma (2 papers, 2016 to 2022). A carcinoma that arises from the intrahepatic biliary tree (intrahepatic cholangiocarcinoma) or from the junction, or adjacent to the junction, of the right and left hepatic ducts (hilar cholangiocarcinoma). "Generally, IL-6 was secreted by noncancer stem cells in low-attachment culture conditions and enriched Oct4 gene expression by activating the IL-6R/JAK/STAT3 signaling pathway in chronic inflammatory disease, such as cholangiocarcinoma." (PMID 27809873, 2016).
Chronic hepatitis B (2 papers, 2011 to 2012). "Taken together, these data suggested that modulation of IL-6R expression on CD4+ T cells is an important mechanism underlies the enhanced Th17 responses in patients with chronic hepatitis B." (PMID 21639870, 2011). "To validate whether enhanced IL-6R expression on CD4+ T cells is causative of elevated Th17 response in patients with chronic hepatitis B, we studied the effect of blockade of IL-6R signaling on PMA/ionomycin and HBcAg induced IL-17 production by purified CD4T cells in vitro." (PMID 21639870, 2011).
colorectal tumor (2 papers, 2019). "While it was demonstrated that colorectal tumor formation requires cleavage of IL-6R by ADAM17 to mediate soluble (s)IL-6R-dependent IL-6 trans-signaling, it further underlines the significance of ADAM17 in CRC pathology." (PMID 31060243, 2019). "The oncogenic role of IL6R in mediation of colorectal tumour invasion via activation of EMT was demonstrated though modulation of the IL-6R/STAT3/miR-34a feedback loop." (PMID 30857282, 2019).
cystic fibrosis (2 papers, 2016 to 2020). Autosomal recessive disorder caused by pathogenic variants in the CFTR gene (cystic fibrosis transmembrane conductance regulator), which encodes a chloride and bicarbonate channel expressed in epithelial cells, and follow the diagnosis criteria. "The IL-6R expression by activated fibroblasts was already demonstrated in other inflammatory states and here we report its involvement in the cystic fibrosis lung stroma." (PMID 32492951, 2020).
dementia (2 papers, 2021 to 2023). Loss of intellectual abilities interfering with an individual's social and occupational functions. "Since neurons do not express the IL-6 receptor, we speculate that the IL-6/IL-6R trans-signaling pathway via gp130 on neurons may be critical in mediating cognition-relevant neuronal damage, similar to what has been described in a mouse model of dementia." (PMID 34711238, 2021).
diverticulitis (2 papers, 2015 to 2019). An infection that develops in the diverticula of the intestinal tract. "One exception is tocilizumab, a humanized anti-human interleukin-6 receptor antibody, which may cause intestinal perforation; it is contraindicated in older patients and patients with history of diverticulitis." (PMID 26064129, 2015).
emphysema (2 papers, 2017 to 2024). "Classic IL-6 signaling through membrane-bound IL-6R has been associated with regenerative activities, whereas trans-signaling has been related to proinflammatory activities and blocking trans-signaling in an emphysema mouse model, where it suppressed alveolar cell apoptosis." (PMID 38302925, 2024). "Based on this and previous work, the authors hypothesized that IL-6R trans-signaling may contribute to lung inflammation and the development of emphysema via two discrete pathways." (PMID 28334838, 2017).
Fever (2 papers, 2019 to 2025). Body temperature elevated above the normal range. "The dispersion estimates results showed that the difference in the expression of IL6R, TNF-α and PTGS2 between the normal group and the fever group was statistically significant (p < 0.01)." (PMID 40430430, 2025). "Compared with the normal group, the expression levels of IL6R, TNF-α, and PTGS2 were significantly higher in the fever group (p < 0.01)." (PMID 40430430, 2025).
fibromyalgia (2 papers, 2023 to 2026). A chronic disorder of unknown etiology characterized by pain, stiffness, and tenderness in the muscles of neck, shoulders, back, hips, arms, and legs. "The characteristic hypersensitivity to mechanical and thermal stimuli in fibromyalgia was significantly reduced by the IL-6-R-Ab administration." (PMID 36979771, 2023). "The analgesic effect of the IL-6-R-Ab administration on the long-term fibromyalgia-induced changes in the nociceptive pathways persisted." (PMID 36979771, 2023). "Firmly in line with the literature, the increase in chemokines in the animals with fibromyalgia was correlated with increased Iba1 expression, while the IL-6-R-Ab administration significantly reduced microglial activation." (PMID 36979771, 2023). "Furthermore, STAT3 has a key role in nociceptive transmission; in our study, the inhibition of the Jak/STAT3 pathway by the IL-6-R-Ab administration reduced the pain-like behaviors induced by fibromyalgia." (PMID 36979771, 2023). "In order to investigate the effects of IL-6-R Ab on fibromyalgia, the rats were subcutaneously administered reserpine for three consecutive days and were intraperitoneally injected at seven days after the first reserpine injection with IL-6-R Ab 1.5 mg/kg." (PMID 36979771, 2023).
gallbladder cancer (2 papers, 2023 to 2024). "In addition, IL-6Rα was found to be downregulated in another bile duct cancer and gallbladder cancer, and low IL-6Rα expression correlated with poor OS." (PMID 38881895, 2024).
HCMV infection (2 papers, 2013 to 2024). "Indeed, our transcriptome analysis revealed a specific enrichment of the IL-6/JAK-STAT3 signaling pathway in HCMV-infected RPTECs, which led us to demonstrate that exposure to the IL-6R inhibitor TCZ can significantly disrupt the paracrine inflammatory loop elicited by HCMV infection." (PMID 38459109, 2024). "HCMV infection induced STAT3 activation in both cell types, whereas incubation of HCMV-infected cells with an IL-6R neutralizing antibody decreased STAT3 phosphorylation." (PMID 23555719, 2013).
hip fracture (2 papers, 2023 to 2026). Traumatic or pathological injury to the hip in which the continuity of either the femoral head, femoral neck, intertrochanteric or subtrochanteric regions is broken. "A significant gene-gene interaction between ESR1 (rs2228480) and RANK (rs3018362) increased osteoporosis risk (OR = 2.1 [1.4-3.2], CVC = 10/10), and a gene-gene model involving ESR1, IL6R, IL1β, and RANKL was identified for hip fracture (CVC = 8/10)." (PMID 41929826, 2026).
injury (2 papers, 2021 to 2022). Damage inflicted on the body as the direct or indirect result of an external force, with or without disruption of structural continuity. "The present study found that the IL-6 expression in PrL was significantly increased on weeks 5 after SNI, and the knockdown of IL-6R in pyramidal neuron of PrL relieved the depression-like behavior induced by nerve injury." (PMID 35690777, 2022).
insomnia (2 papers, 2014 to 2024). A sleep disorder characterized by difficulty in falling asleep and/or remaining asleep. "SKK also regulates plasma interleukin-6 and soluble interleukin-6 receptor concentrations and improves depressed mood in climacteric women with insomnia." (PMID 24790634, 2014).
intestinal polyp (2 papers, 2021). Discrete abnormal tissue masses that protrude into the lumen of the intestine. "After IL-6R antibody treatment for 10 weeks, the anti-IL6-R-treated Apcmin/+Ripk3-/- mice showed fewer intestinal polyps than UT Apcmin/+Ripk3-/- mice." (PMID 33996591, 2021). "After IL-6R antibody treatment for 10 weeks, the anti-IL6R-treated Apcmin/+Mlkl-/-mice exhibited fewer intestinal polyps than the UT Apcmin/+Mlkl-/-group." (PMID 33767595, 2021).